ACSL4 (acyl-CoA synthetase long chain family member 4)
Diseases named in the same sentence as ACSL4 in open-access papers (continued):
Sharing a sentence is not in itself a finding about the gene and the disease.
varicocele (1 paper, 2024). A condition characterized by the dilated tortuous veins of the spermatic cord with a marked left-sided predominance. "Interestingly, the seminal testosterone level was significantly decreased (p < 0.05) in the group with urogenital infections; in patients with urogenital infections or varicocele, the sperm ACSL4 concentration was significantly increased (p < 0.05) compared with that observed in the fertile group." (PMID 39273059, 2024). "In our study, the decreased level of testosterone concomitant with increased ACSL4 concentration, and similar levels of GPX4, could suggest a GPX4-independent pathway of ferroptosis in the presence of varicocele and urogenital infection." (PMID 39273059, 2024).
tumor (289 papers, 2011 to 2026). "This study uncovers COP1 as a novel E3 ubiquitin ligase in RCC that targets ACSL4 for K48-linked ubiquitination and degradation, thereby suppressing ferroptosis and driving tumor progression." (PMID 40395328, 2025). "As a central ferroptosis regulator, ACSL4 is highly expressed in ferroptosis-prone cells, influencing tumor cell susceptibility to ferroptosis." (PMID 40860143, 2025). "Various compounds or genes such as Fatty-Acid-Coenzyme A Ligase, Long-Chain 4 (ACSL4) associated with lipid metabolism can modulate ferroptosis in tumor cells, highlighting the associations of lipid metabolism and ferroptosis sensitivity." (PMID 41444950, 2025). "While ACSL4 promotes ferroptosis to eliminate tumor cells, its upregulation also suggests a pathogenic role in ferroptosis-associated diseases." (PMID 40932861, 2025). "The CCK-8 assay revealed that knockdown ACSL4 partially reversed tumor cell death caused by UNC1999 combined with erastin in 786-O and ACHN." (PMID 41372608, 2025). "It has been reported that ACSL4 is crucial for the development and progression of cancers, with its up-regulation clearly associated with tumor growth, recurrence, metastasis, and therapy resistance." (PMID 38564125, 2025). "This pathway operates independently of GPX4 and ACSL4 and has been demonstrated to suppress tumor formation, as the loss or mutation of ALOX12 accelerates cancer development in lymphoma models." (PMID 40733290, 2025). "Phosphorylation of ACSL4 by mitochondria-located metabolic kinase PCK2 is critical to regulating ferroptosis-associated phospholipid remodeling in tumor-repopulating cells that are resistant to chemotherapy and radiotherapy." (PMID 38720107, 2024). "Ferroptosis induction, particularly through the RB/E2F/ACSL4 axis, emerges as a promising strategy for combating tumor growth driven by RB1 loss, offering potential clinical benefits in various cancer types." (PMID 38672640, 2024). "The results of the present study indicated that high ACSL4 levels were significantly associated with the extrahepatic type, the tumor growth type, and high ALT levels in CCA." (PMID 39335604, 2024). "In tumor cell, tumor suppressor gene RB1 mutation upregulates the levels of ACSL4 and enriches ACSL4-dependent arachidonic acid–containing (AA–containing) phospholipids which increase tumor cell vulnerability to ferroptosis." (PMID 38396022, 2024). "High ACSL4 expression levels showed a trend towards an association with the extrahepatic (p = 0.05) and mixed tumor growth (p = 0.06) types of CCA." (PMID 39335604, 2024). "The results of the present study demonstrated a significant association between high ACSL4 levels and the extrahepatic and tumor growth types of CCA, as well as elevated levels of ALT." (PMID 39335604, 2024). "In a clinical context, the presence of tumor ACSL4 is associated with T cell markers and improved survival in cancer patients treated with immune checkpoint blockade (ICB) therapy." (PMID 37894808, 2023). "And the detection of ferroptosis‐associated markers in xenograft tumor samples with USP5 overexpression also showed that ACSL4 decreased, and SLC7A11 increased." (PMID 37492786, 2023). "We also evaluated the association between ACSL4 expression and tumor-infiltrating immune cells in the TIMER database." (PMID 35126480, 2022). "After adjusting for tumor purity, ACSL4 expression was strongly associated with 57 of 58 BRCA immune cell markers, 41 of SKCM, and 24 of LIHC." (PMID 35126480, 2022). "In an HCC model of chronic liver injury, loss of ACSL4 significantly impaired the progression of tumor growth, accompanied by lower levels of tissue fibrosis and proliferation." (PMID 36238649, 2022). "Radiation can induce ferroptosis by creating ROS, depleting glutathione, activating genes linked to DNA damage and increasing the expression of acyl-CoA synthetase long-chain family member 4 (ACSL4) in tumor cells." (PMID 36176274, 2022).
tumor (continued). "ACSL4 inhibition is associated with diminished necrosis areas and a less aggressive tumour behaviour." (PMID 35208642, 2022). "Our study found a tight association between ACSL4 and tumor-related lymphocytes, including CD8+ T cells." (PMID 34868963, 2021). "Elevated ACSL4 was associated with suppressed tumor progression and better outcomes for BLCA patients." (PMID 34868963, 2021). "ACSL4 was previously associated with the colon carcinogenesis; it was associated with tumor cell growth in liver cancer and was described as an independent prognostic factor in patient tissue analysis." (PMID 33050166, 2020). "Research indicates that ACSL4 upregulation in TNBC is also closely linked to tumor metastasis." (PMID 40510158, 2025). "Experimental evidence shows that genetic knockout of PKCβII or ACSL4, or site‐specific mutation blocking ACSL4 phosphorylation, significantly suppresses ferroptosis and T cell‐mediated tumor immune killing, ultimately driving resistance to PD‐1 inhibitor therapy." (PMID 40919133, 2025). "Overexpression of ACSL1 and ACSL4 has been linked to enhanced tumour aggressiveness." (PMID 41154605, 2025). "Moreover, key ferroptosis factors GPX4 and ACSL4 are closely associated with multiple tumor-related signaling pathways, including tumor proliferation, EMT, angiogenesis, and tumor inflammation pathways." (PMID 39335103, 2024). "Moreover, AMPK regulates Nrf2 degradation and ARE transcription, downregulates stearoyl-coenzyme A desaturase-1 and synergizes with acyl-CoA synthetase long-chain family member 4 (ACSL4) to make tumor cells susceptible to ferroptosis." (PMID 36275899, 2022). "Ferroptosis is a recently-defined tumor suppression mechanism, but the sensitivity of many tumorigenic cells to ferroptosis is limited by their deficient expression of acyl-CoA synthetase long-chain family member 4 (ACSL4)." (PMID 36517470, 2022). "ACSL4 may be a promising prognostic biomarker for pan-cancer and is closely associated with immune infiltration in the tumor microenvironment." (PMID 35126480, 2022). "Moreover, transcript levels of genes associated with CRC susceptibility loci (e.g., Grem1 and Bmp4) and tumor development and invasion (e.g., Wnt5a, Ereg, Mmp3, Mmp13, Timp1, Saa3, Ptgs2, and Acsl4) were elevated in IL-11+ fibroblasts." (PMID 33863879, 2021). "The unique subcellular localization of ACSL4 to peroxizomes and mitochondria-associated endoplasmic reticulum membranes suggests a possible role for this enzyme in facilitating oxidation of free fatty acids as a source of energy in proliferating tumor cells." (PMID 24155918, 2013). "Higher ACSL4 expression was also associated with TNBC tumor samples." (PMID 24155918, 2013). "Thus, ACSL4 overexpression is important in the promotion of the cell’s characteristics associated with cancer progression including increased proliferation and tumor growth promotion." (PMID 22808264, 2012). "Through these multilayered regulatory mechanisms, ACSL4 integrates lipid remodeling with ferroptotic sensitivity and tumor-immune interactions within the tumor microenvironment." (PMID 42064086, 2026). "Key lipid enzymes and ferroptosis regulators such as MAGL, ACSL4, and xCT modulate tumor survival and therapy response." (PMID 41710656, 2026). "ACSL4 levels also correlated with greater immune cell infiltration within the tumor microenvironment." (PMID 41918944, 2026). "As expected, Western blot results showed that the protein expression of ACSL4 in the tumor tissues of shACSL4 mice was also down-regulated, compared with that of shCtrl mice." (PMID 38564125, 2025). "Specifically, IFN-γ activates the JAK/STAT1/interferon regulatory factor 1 (IRF1) signaling pathway to upregulate ACSL4 transcription in tumor cells by promoting IRF1 binding to ACSL4 promoter region IFN-stimulated response elements." (PMID 40169575, 2025).
tumor (continued). "This is believed to represent the initiating mechanism of ferroptosis in tumor cells, with ACSL4 as a critical node in lipid metabolism pathways." (PMID 40919133, 2025). "In this study, it was first determined the high expression of ACSL4 in OS tissues compared to para-carcinoma tissues and shed light on the positively correlation between the expression level of ACSL4 and tumor stages of OS patients." (PMID 38564125, 2025). "IRF1, in turn, binds to the promoter region of ACSL4, upregulating its expression, thereby facilitating lipid peroxidation and ferroptosis in tumor cells." (PMID 40285867, 2025). "ACSL4 has been shown to promote tumor cell metastatic extravasation and colonization by enhancing plasma membrane fluidity." (PMID 41288931, 2025). "During BC progression, ACSL4 acts as a tumor-suppressive regulator through its pro-ferroptotic activity." (PMID 41288931, 2025). "Exogenous arachidonic acid enhances RSL3-mediated ferroptosis, while CAR-T cells engineered to secrete IFN-κ induce tumor ferroptosis via an IFNAR/STAT1/ACSL4 axis." (PMID 39849645, 2025). "Specifically, we observed a significant down-regulation of some of the most relevant genes in the PPAR pathway (CD36, FABP4, PLIN1, PLIN4, SCD5 and ACSL4) in tumor tissue samples." (PMID 40860798, 2025). "Mechanistically, the produced IFN-γ synergizes with arachidonic acid to trigger Acsl4-mediated tumor ferroptosis." (PMID 41254669, 2025). "have revealed that another type I family member IFN‐κ also drives tumour ferroptosis in combination with AA via the IFNAR/STAT1/ACSL4 axis." (PMID 40045458, 2025). "In vivo, COP1 overexpression accelerated tumor growth in xenograft models, with a 2.5-fold increase in tumor volume compared to controls (p < 0.001), accompanied by reduced ACSL4 expression and elevated Ki67 proliferation index." (PMID 40395328, 2025). "Targeting ACSL4 compromised the effect of BQ in modulating ATP production, thus suppressing tumor growth." (PMID 40507798, 2025). "Tumor tissues from the CIRT group exhibited increased ferroptosis marker ACSL4 and reduced GPX4 expression, consistent with in vitro findings." (PMID 40917841, 2025). "This inhibition of ACSL4-driven ferroptosis promotes tumor progression and confers resistance to sunitinib therapy." (PMID 40395328, 2025). "Overexpression of miR-145-5p or silencing of ACSL4 notably inhibited tumor growth in terms of volume and weight." (PMID 39652084, 2025). "Depending on the tumor type and tissue environment, ACSL4 can exert either pro- or antitumorigenic effects." (PMID 39984452, 2025). "Recently, ACSL4 was found to mediate metastatic extravasation of metastasis-derived tumor cells by enhancing membrane fluidity." (PMID 41188993, 2025). "The overexpression of key enzymes such as Acyl-CoA Synthetase Long Chain Family Member 4 (ACSL4), FASN, and HMG-CoA in TNBC cells is strongly associated with tumor proliferation and metastasis." (PMID 40510158, 2025). "ACSL4 plays a dual role in MM: it promotes tumor growth by activating lipid synthesis, but also initiates ferroptosis by catalyzing the production of PUFA-CoA, a key substrate for lipid peroxidation." (PMID 40735482, 2025). "Sh‐YTHDF2 and DNase I inhibited GPX4, SLC7A11, and FTH1 expression in the tumour, while increasing ACSL4 and PTGS2 levels and had a superimposed effect." (PMID 39865544, 2025). "Interferon-gamma (IFN-γ) regulates the expression of SLC3A2, SLC7A11, and ACSL4, subsequently inducing immunogenic ferroptosis in tumor cells." (PMID 40260246, 2025). "A significant down-regulation of CD36, FABP4, PLIN1, SCD5 and ACSL4 in tumor samples has also been validated by RT-qPCR." (PMID 40860798, 2025). "Studies have shown that IR can induce the expression of ACSL4, thereby triggering ferroptosis in tumor cells." (PMID 40050614, 2025).
tumor (continued). "As intercellular communication carriers, exosomes can transport signaling molecules related to ferroptosis (such as miRNAs, GPX4, ACSL4, iron metabolites, etc.), reflecting tumor progression, prognosis, and treatment sensitivity." (PMID 40328736, 2025). "PDP2 induces ferroptosis in tumor cells by dephosphorylating and inhibiting the Acyl-CoA Synthetase Long-Chain Family Member 4 (ACSL4) activity." (PMID 40746885, 2025). "The biological role of Acyl-CoA synthetase long-chain family member 4 (ACSL4), recently identified as an oncogene in numerous tumor types, remains largely unclear in OS." (PMID 38564125, 2025). "Collectively, dysregulated expression of ACSL1, ACSL4 and ACSL5 isoforms in CRC tissues is associated with tumour progression and patient outcomes, warranting additional research for biomarker development." (PMID 41154605, 2025). "This enhancement promoted the expression of acyl-CoA synthetase long chain family member 4 (ACSL4), which in turn strengthened the overall anti-tumor response." (PMID 39849645, 2025). "Here, ACSL4 promotes ferroptosis by increasing lipid peroxidation, thereby enhancing anti-tumor efficacy in NSCLC." (PMID 41288931, 2025). "Compared to the sh-NC group, the sh-LINC00958 group showed decreased LINC00958 expression and GPX4 expression in the tumor tissue (p < 0.05), along with elevated iron content, ROS levels, and ACSL4 expression, and reduced GSH levels (p < 0.05)." (PMID 40537877, 2025). "Our study findings support BQ323636.1 (BQ), a splice variant of NCOR2, as a key orchestrator of such metabolic reprogramming, driving lipid metabolism via ACSL4 to support tumor growth, survival, and resistance in ER-positive breast cancer." (PMID 40507798, 2025). "This platform ind uces immunogenic ferroptosis—a form of programmed cell death—while upregulating AA expression to enhance ACSL4-mediated tumor cell death, synergizing with CD8+ T cell-derived IFN-γ to boost anti-tumor immunity." (PMID 41210682, 2025). "Conversely, one study suggests that upregulation of ACSL4 exerts an antiproliferative effect in GBM by promoting ferroptosis, thereby positioning ACSL4 and ferroptosis as tumor-protective factors." (PMID 41288931, 2025). "Knockdown of ACSL4 leaded to radioresistance by inhibiting ferroptosis, while overexpression of ACSL4 enhanced radiosensitivity by promoting ferroptosis in tumor cells." (PMID 40050614, 2025). "ACSL4 stimulated by IFN-γ can change the lipid pattern of tumor cells, thereby enhancing the incorporation of arachidonic acid (AA) into C16 and C18 acyl chain-containing phospholipids." (PMID 40539046, 2025). "The expression levels of ACSL4 and SLC7A11 are important biomarkers for determining the ferroptosis sensitivity of CCA cells, with high expression often associated with tumor progression and poor prognosis." (PMID 41201667, 2025). "ACSL4 expression was significantly higher in HCC than in all other tumour types, while ACSL3 expression was similar in HCC and hepatic metastases." (PMID 41154605, 2025). "It is noteworthy that CD8+ T cells are significantly more sensitive to GPX4 inhibition than tumor cells: ACSL4 knockdown significantly reduces ferroptotic cell death, while FSP1 overexpression provides protection through the CoQ10 regeneration pathway." (PMID 40535125, 2025). "PCK2 was found to be downregulated in tumor‐repopulating cells and empowered resistance to ferroptosis in an ACSL4‐dependent manner." (PMID 39811936, 2025). "Afterward, the biological effects of ACSL4 knockdown on the cell proliferation, apoptosis, cell cycle, and migratory potential in vitro, as well as tumor growth in vivo were investigated using both in vitro and in vivo models." (PMID 38564125, 2025). "Radiotherapy significantly induced the expression of ACSL4, which in turn promoted ferroptosis of tumor cells, increased the sensitivity of tumors to radiotherapy, and effectively inhibited tumor growth." (PMID 41293165, 2025).